PANTR1 (POU3F3 adjacent non-coding transcript 1)
Synonyms: linc-Brn1a; linc-POU3F3; LINC01114; LINC01158; PANCAT
Gene: Long non-coding RNA gene on chromosome 2 (104,656,012 to 104,857,008, reverse strand). Ensembl gene ENSG00000233639.
Diseases named in the same sentence as PANTR1 in open-access papers:
PANTR1 is named in the same sentence as 16 diseases in open-access papers, as found by Europe PMC text mining. Sharing a sentence is not in itself a finding about the gene and the disease. The quoted sentences say what the papers report.
glioma (6 papers, 2020 to 2025). A benign or malignant brain and spinal cord tumor that arises from glial cells (astrocytes, oligodendrocytes, ependymal cells). "The in-vitro study showed that the knockdown of PANTR1 caused significantly reduced glioma cells viability." (PMID 36861062, 2023). "On the molecular level, low expression of PANTR1 caused significantly reduced glioma cell viability and enhanced cell death." (PMID 36861062, 2023). "In the glioma samples of this study, 212 genes (red dots) were found to have closed correlations with PANTR1, while 170 genes (blue d-ots) were negatively associated." (PMID 36861062, 2023). "The receiver operating characteristic (ROC) curve of the nomogram indicated that PANTR1 could serve as a potential diagnostic parameter for gliomas (AUC of 0.958)." (PMID 36861062, 2023). "Moreover, R-loops in Pou3f3/Brain-1 extended into the neighboring Pantr1 (Pou3f3 adjacent non-coding transcript 1) gene, which encodes a long non-coding RNA implicated in glioma development." (PMID 35927309, 2022). "In conclusion, this study provides the first evidence that PANTR1 has a relevant role in human glioma by influencing cell viability and cell death." (PMID 36861062, 2023). "After PANTR1 knockdown, we observed different degrees of cell growth and cell death in cell lines, which was more pronounced in low-grade glioma cells." (PMID 36861062, 2023). "We evaluated the role of PANTR1 in glioma cells using published data from The Cancer Genome Atlas (TCGA), then validated it by ex vivo experiments." (PMID 36861062, 2023). "Reverse transcription-quantitative (RT-q) PCR showed that all the 15 glioma samples' PANTR1 expression outweighs normal adjacent tissues, whereas grade II and III glioma tend to have a higher expression rather than GBM compared with NAT (supplement 10)." (PMID 36861062, 2023). "The functions of lncRNA POU3F3 adjacent noncoding transcript 1 (PANTR1) have been investigated in hepatocellular carcinoma but remain yet unclear in gliomas." (PMID 36861062, 2023). "To investigate the potential cellular mechanism of different levels of PANTR1 expression in glioma cells, we used siRNA-mediated knockdown in low-grade (grade II) cell lines and GBM (grade IV) cell lines (SW1088 and SHG44, respectively)." (PMID 36861062, 2023). "The result showed that Ser473 phosphorylated Akt1 expression by the western blot was markedly reduced in PANTR1 knockdown glioma cells, which plays an important role in cell death." (PMID 36861062, 2023). "In the present study, cell invasion assays showed decreased invasiveness in both SW1088 and SGH44 glioma cell lines after PANTR1 knockdown, which were consistent with the results in other tumor types." (PMID 36861062, 2023). "The role of lncRNAs in tumorigenesis is receiving increasing recognition, our study provides insight into future therapeutic targets for gliomas, and we believe that further studies are still needed to further establish the role of PANTR1." (PMID 36861062, 2023). "Of note, high expression of PANTR1 was associated with poor OS (HR = 2.04, 95% CI: 1.39–2.99, p < 0.001) in patients with WHO grade II and III gliomas." (PMID 36861062, 2023). "In the current study, we first found the mRNA level of PANTR1 increased in glioma samples by a public dataset mining and verified by (RT-q) PCR of collected glioma samples." (PMID 36861062, 2023). "So far, several studies have identified PANTR1 as an oncogenic driver in different types of cancer such as esophageal squamous cell cancer (eSCC), glioma, hepatocellular carcinoma, cervical, colorectal, gastric, prostate and breast cancer." (PMID 32397610, 2020). "Moreover, we identified the importance of PANTR1 expression for cell migration in both cell lines, a critical foundation for invasiveness in recurrent gliomas." (PMID 36861062, 2023). "Thus, the present study aimed to explore a novel interactome, PANTR1, and to discover the inner relationship between PANTR1 and gliomas." (PMID 36861062, 2023).
glioma (continued). "Further analysis confirmed a significantly higher expression of PANTR1 in glioma tissues." (PMID 36861062, 2023). "To figure out whether PANTR1 affects glioma patients' prognosis, we used Kaplan–Meier survival analysis." (PMID 36861062, 2023). "To elucidate whether PANTR1 is involved in glioma, we compared the expression of PANTR1 in normal adjacent to tumor (NAT) tissues and tumor tissues." (PMID 36861062, 2023). "Meanwhile, the result of WB indicated that PI3K-Akt pathway signaling might be involved in glioma progression regulated by PANTR1." (PMID 36861062, 2023). "In the present study, PANTR1 was found to be significantly up-regulated in glioma tissues." (PMID 36861062, 2023). "Kaplan–Meier survival analysis showed high PANTR1 expressed gliomas indicate poor prognosis." (PMID 36861062, 2023). "In addition, a major inhibition of cell viability (G2 phase blockage in the cell cycle), migration, and invasiveness was found in PANTR1 knock-out glioma cells." (PMID 36861062, 2023). "Considering PANTR1 has previously been reported to be associating with tumorigenesis of hepatocellular carcinoma, we hypothesize that PANTR1 may play a significant role in glioma tumorigenesis." (PMID 36861062, 2023). "The result suggests that PANTR1 was correlated with a poor prognosis among glioma patients." (PMID 36861062, 2023). "Based on the previously reported results of PANTR1 regarding its angiogenic potential in glioma, we used in vitro angiogenesis models to test the hypothesis that PANTR1 influences angiogenesis." (PMID 32397610, 2020). "As tumor angiogenesis is one of the most critical steps in ccRCC and PANTR1 has been associated with kidney development and tumor angiogenesis in glioma, we hypothesized that PANTR1 might play an important role in ccRCC carcinogenesis." (PMID 32397610, 2020). "Collectively, the nomogram we constructed proved that PANTR1 could serve as a potential biomarker of glioma prognosis, as high expression of PANTR1 may confer a variety of adverse events at the molecular level, especially in those with grade II/III gliomas." (PMID 36861062, 2023).
gastric cancer (5 papers, 2020 to 2023). A primary or metastatic malignant neoplasm involving the stomach. "POU3F3 adjacent non-coding transcript 1(LINC01158; linc-POU3F3; PANTR1) was proved to facilitate colorectal cancer, gastric cancer and hepatocellular carcinoma." (PMID 34044826, 2021).
Clear-Cell Renal Cell Cancer (4 papers, 2020 to 2023). "For example, lncRNA PANTR1 was related to poor prognosis and promoted angiogenesis and apoptosis in clear cell renal cell cancer." (PMID 35440045, 2022). "In clear cell renal cell carcinoma, a knockdown of lncRNA POU3F3-adjacent non-coding transcript 1 (PANTR1) leads to a reduction of angiogenic parameters and less tube formations." (PMID 32992718, 2020). "Some suggested that the combination of PANTR1 with other lncRNAs may identify the early progression of clear-cell renal cell cancer, breast cancer, and cervical cancer." (PMID 36861062, 2023). "In this study, PANTR1 expression was confined to human brain and kidney tissue and was found significantly up-regulated in clear-cell renal cell carcinoma tissue (ccRCC) compared to non-cancerous kidney tissue in two independent cohorts (p < 0.001 for both cohorts)." (PMID 32397610, 2020).
hepatocellular carcinoma (4 papers, 2020 to 2025). A malignant tumor that arises from hepatocytes. "Previous studies demonstrated that Linc-POU3F3 (PANTR1) could promote tumor cell invasion in hepatocellular carcinoma and colorectal cancer." (PMID 36861062, 2023). "RETRACTION: X. Ma, Z. Mao, J. Zhu, H. Liu, F. Chen, lncRNA PANTR1 Upregulates BCL2A1 Expression to Promote Tumorigenesis and Warburg Effect of Hepatocellular Carcinoma through Restraining miR-587, Journal of Immunology Research, 2021." (PMID 40351571, 2025).
cervical cancer (2 papers, 2020 to 2023). A primary or metastatic malignant neoplasm involving the cervix. "Additionally, and in accordance with our ccRCC cohort, PANTR1 alone as well as in combination with other lncRNAs could identify patients with early progress in eSCC, breast and cervical cancer." (PMID 32397610, 2020).
cholangiocarcinoma (1 paper, 2020). A carcinoma that arises from the intrahepatic biliary tree (intrahepatic cholangiocarcinoma) or from the junction, or adjacent to the junction, of the right and left hepatic ducts (hilar cholangiocarcinoma). "It has been shown to inhibit angiogenesis in cholangiocarcinoma —a fact further strengthening a contribution of PANTR1 to angiogenesis." (PMID 32397610, 2020).
kidney cancer (1 paper, 2020). Primary or metastatic malignant neoplasm involving the kidney. "Overall, our data show for the first time that PANTR1 plays a relevant role in human kidney cancer which can be partly explained by its influence on apoptosis and tumor angiogenesis." (PMID 32397610, 2020). "To study the underlying cellular mechanisms mediated by varying levels of PANTR1 in kidney cancer cells, we applied siRNA-mediated knock-down experiments in three independent ccRCC cell lines (RCC-FG, RCC-MF, 769-P)." (PMID 32397610, 2020).
cancer (4 papers, 2020 to 2025). A tumor composed of atypical neoplastic, often pleomorphic cells that invade other tissues. "POU3F3 adjacent noncoding transcript 1 (PANTR1) is an oncogenic long noncoding RNA that is located at 4 kb upstream of the protein-encoding POU3F3 gene that has a substantial influence on a variety of cellular features in various types of cancer." (PMID 36861062, 2023). "POU3F3 adjacent non-coding transcript 1 (PANTR1) is an oncogenic long non-coding RNA with significant influence on numerous cellular features in different types of cancer." (PMID 32397610, 2020). "In all ccRCC cancer cell lines, cellular growth was significantly reduced in cells with decreased PANTR1 expression levels compared to control conditions." (PMID 32397610, 2020). "In a first step, we investigated the influence of PANTR1 on the probably most important trait of cancer cells—their ability of a sustained proliferation." (PMID 32397610, 2020). "PANTR1 apparently plays a role in angiogenesis in other types of cancer." (PMID 32397610, 2020). "To explore whether PANTR1 influences angiogenesis-related factors in ccRCC cancer cells, we measured the gene expression levels of several angiogenetic factors upon PANTR1 knock-down." (PMID 32397610, 2020). "The major role of PANTR1 in renal development and the remarkable impact on different hallmarks of cancer lead us to the hypothesis of PANTR1 playing a noteworthy role in ccRCC carcinogenesis." (PMID 32397610, 2020). "In contrast to its protein-coding neighbor, PANTR1 is furtherly known for its versatile role in carcinogenesis as a promotor of cell migration, invasion, angiogenesis and proliferation as well as a repressor of apoptosis in different types of cancer." (PMID 32397610, 2020). "These cell line findings are corroborated by a positive (though weak) correlation of PANTR1 with VEGF-A (R = 0.19, p < 0.001) and LAMC2 in RCC cancer tissue (R = 0.13, p = 0.0028)." (PMID 32397610, 2020). "RNA in situ hybridization confirmed a specific and higher expression of PANTR1 in cancer cells of RCC tissue compared to luminal cells of non-cancerous kidney tissue." (PMID 32397610, 2020).
tumor (3 papers, 2016 to 2023). "In addition, wound-healing assay that showed a migratory capacity decline of Si-PANTR1 transfected cells suggested PANTR1 is associated with tumor invasiveness and metastasis." (PMID 36861062, 2023). "It was also demonstrated that the CpG island near the PANTR1 gene is highly methylated and that its transcriptional activity is generally inhibited in the process of tumor progression." (PMID 36861062, 2023). "The results showed that expression of PANTR1 was significantly increased in several tumor tissues including GBM." (PMID 36861062, 2023).
PANTR1 also shares sentences with these, for which no sentence is quoted: breast carcinoma (3 papers); colorectal cancer (2); esophageal squamous cell carcinoma (1); glioblastoma (1); nasopharyngeal carcinoma (1); non-small cell lung carcinoma (1); prostate carcinoma (1).